H2AX (H2A.X variant histone)
Diseases named in the same sentence as H2AX in open-access papers (continued):
Sharing a sentence is not in itself a finding about the gene and the disease.
breast carcinoma (continued). "Similarly, another study reported the correlation between immunofluorescence of γ- H2AX/53BP1 residual in breast cancer patients with healthy volunteers." (PMID 33013205, 2020). "Besides, H2AX was activated in response to BA treatment, reflected by the presence of double-strand DNA breaks in breast cancer cells." (PMID 31531187, 2019). "In conclusion, we have characterized the biological effects of SUV39H2 inhibition by OTS193320 in vitro on breast cancer cell viability and γ-H2AX regulation, and further demonstrated the in vivo growth suppressive efficacy of OTS186935 in breast and lung cancer models without any visible toxicity." (PMID 30159125, 2018). "This compound, OTS193320, attenuated γ-H2AX levels when used in combination with doxorubicin (DOX) compared with the DOX treatment alone, and caused a significant reduction in breast cancer cell viability when compared to the treatment with a single agent, OTS193320 or DOX." (PMID 30159125, 2018). "Breast cancer cell lines were incubated with physiological levels of cortisol and NE in the presence and absence of receptor antagonists and inducible nitric oxide synthase (iNOS) inhibitors and DNA damage measured using phosphorylated γ-H2AX." (PMID 28340615, 2017). "Furthermore, a reduction in H2AFX gene copy number was verified in MCF7 breast cancer cell line and higher methylation status of H2AFX promoter leads to a reduction of H2AX expression in lung squamous cancer." (PMID 25003966, 2014). "The γ-H2AX assay may have potential for screening individual radiosensitivity of breast cancer patients." (PMID 23617930, 2013). "Furthermore, γ-H2AX has been reported as a prognostic factor in several other types of cancers, including breast cancer, hepatocellular carcinoma, lung cancer, and colorectal cancer, in which γ-H2AX overexpression has been associated with poor patient survival." (PMID 34372868, 2021). "Compared with parental sham-treated cells, radioresistant breast cancer cells present elevated radioresistance, enhanced malignancy, increased expression of Ataxia-telangiectasia mutated (ATM), and increased DNA damage repair efficiency, as reflected by accelerated γ-H2AX kinetic." (PMID 32174787, 2020). "It was found that women with breast cancer had higher relative abundance bacilli, staphylococci, and E. coli, isolated from breast cancer patients, and they demonstrated induction of DNA at double-stranded breaks in HeLa cells by using histon-2AX (H2AX) phosphorylation (γ-H2AX) assay." (PMID 32908523, 2020). "Furthermore, BP enhanced the radiosensitivity of breast cancer cells, which was measured by the colony formation assay and comet assay, where the foci of γ-H2AX after radiation significantly increased in BP pretreated cells and was evidenced by immunocytochemistry staining and western blot." (PMID 29370116, 2018). "In the past decade, H2AX has generated much scientific interest, not only because of its functional enormity but also because of its localization in highly vulnerable cytogenetic regions, such as 11q23.3, which is known to undergo frequent alteration in most human cancers, including breast cancer." (PMID 21463514, 2011). "In murine 4T1 breast carcinoma cells, CFZ treatment prior to irradiation significantly reduced clonogenic survival (dose enhancement factor = 1.26) and increased γ-H2AX foci retention, indicating impaired DNA double-strand break repair." (PMID 41699819, 2026).
breast carcinoma (continued). "Proguanil treatment upregulated apoptotic markers (Bax, p-H2AX, cleaved-caspase 3, 9, cleaved PARP) and downregulated anti-apoptotic proteins (bcl-2, survivin) in breast cancer cell lines." (PMID 38473234, 2024). "In order to elucidate the potential genotoxic mechanism exhibited by PK083, PK9320 and PK9323, histone H2AX phosphorylation and Comet assays were conducted after exposure of MCF-7 breast cancer cells to each of the molecules." (PMID 33810274, 2021). "In a study with diverse cancer-derived cell lines, Koo and colleagues demonstrated that miR-200c overexpression in the breast cancer cell line, MDA-MB-468 provoked an increase of gamma-H2AX foci and prolonged focus formations after irradiation." (PMID 34804940, 2021). "In our standard-of-care therapy resistant ER+ breast cancer cells, treatment with AZD1775 increased gamma-H2AX as a single agent but this signal was diminished when AZD1775 was combined with E2-deprivation/fulvestrant and ribociclib." (PMID 34277427, 2021). "In general, the normal fibroblasts showed quicker phosphorylation of H2AX and recruitment of MRE11 to γH2AX clusters compared to breast cancer cells and a shorter time interval of increased similarity for γH2AX clusters." (PMID 34771723, 2021). "Our results showed that TAIII activated the DDR pathway (ATM/Chk2/Cdc25C) and γ-H2AX quickly, indicating that TAIII induces DNA damage in breast cancer cells." (PMID 33628174, 2020). "miR-24 is regarded to as an oncogenic miRNA in various types of cancer because not only it targets DNA repair genes, such as H2AX but it has also been found upregulated in OSCC, hepatocellular carcinoma, glioblastoma and breast cancer." (PMID 26967561, 2016). "The knockdown of CtIP in breast cancer MCF7 cells reduced Rad51 foci numbers and enhanced f H2AX foci formation after f-irradiation, suggesting that deficiency of CtIP decreases homologous recombination repair and delays DNA double strand break repair." (PMID 26713604, 2016). "Treating breast cancer cell lines with both Olaparib and KU55933 led to significantly more γ-H2AX foci formation than treating them with either inhibitor alone based on fluorescence microscopy." (PMID 27613518, 2016). "In order to confirm this decrease in γ-H2AX levels, IF microscopy was performed in HCC1806 breast cancer cells." (PMID 26459286, 2015). "We have also investigated the ability of MTZ, vit C, and of their combination, in modulating the activation pathways of H2AX and PI3K on both breast cancer cells." (PMID 25531443, 2014). "The p21-dependent downregulation of H2AX was seen both in cell culture and the MMTV-neu mouse model of Her2-positive breast cancer." (PMID 25252808, 2014). "Using immunostaining, we assessed spontaneous and radiation-induced foci of γ-H2AX and 53 BP1 in peripheral blood mononuclear cells derived from unselected breast cancer (BC) patients (n=57) undergoing radiotherapy (RT)." (PMID 23617930, 2013). "Conditioned medium from naïve by stander cells, i.e., cells not exposed to irradiated cells, could mitigate UV-induced DNA damages in human breast carcinoma MCF7 cells, as judged by phospho-H2AX and 53BP1 immunostaining." (PMID 40007574, 2025). "In vitro evaluations included stability assays, cellular uptake (flow cytometry), cytotoxicity (MTT assay), mitochondrial membrane potential (JC-1 staining), apoptosis (Annexin V/PI), DNA damage (γ-H2AX immunofluorescence), and cell cycle analysis in BT549 breast cancer and MCF-10A normal cells." (PMID 40463872, 2025). "Thus, we treated ovarian and breast cancer cell lines with GCH1 inhibitor DAHP and analyzed γ-H2AX foci formation." (PMID 36793373, 2023). "According to the γ-H2AX protein expression level before binding, the sea cucumber saponin monomer STC2 may promote the apoptosis of breast cancer cells by stimulating the regulation of DNA damage response-related proteins." (PMID 35607324, 2022).
breast carcinoma (continued). "Concordant to the western blotting, we observed significant reduction in γ-H2AX in the combination therapy compared with DOX mono-treatment, further supporting that OTS193320 plays a critical role in the regulation of γ-H2AX formation in breast cancer cells." (PMID 30159125, 2018). "Furthermore, the combination therapy reduced γ-H2AX levels in breast cancer cells, and further attenuated the formation of 53BP1/γ-H2AX foci, supporting that OTS193320 regulates the production of γ-H2AX in cancer cells." (PMID 30159125, 2018). "To examine whether OTS193320 can regulate the formation of γ-H2AX in MDA-MB-231 and BT-20 breast cancer cells, we investigated this compound as a single agent and in combination with DOX." (PMID 30159125, 2018). "Our results show that combined supplementations of vit C and MTZ have cytotoxic effect by apoptotic death, a mild G2/M elongation and activation of H2AX and mild PI3K pathways, and, hence, can be really useful for improving the chemotherapy treatments on breast cancer." (PMID 25531443, 2014). "Furthermore, we also detected the level of DNA damage in breast cancer cells overexpressing RUVBL1 after radiation treatment, and the results showed that overexpressing RUVBL1 significantly reduced the expression level of γ-H2AX protein in breast cancer cells." (PMID 38609375, 2024). "The level of autophagy in MCF7 breast cancer (BC) cells can be increased by mTOR inhibitor, rapamycin (RAPA), delayed the attendance of Rad51 and BRCA1 protein localization, and prolonged the expression of damage characteristic sensor γ-H2AX, resulted in the accumulation of DSB damage." (PMID 34321364, 2021). "We also observe an increase in Ser139 phosphorylation of histone H2AX (γH2AX), a histone modification that can accompany DNA damage, apoptosis, X chromosome inactivation, and/or mitosis in the four breast cancer cell lines, but not MCF10A cells." (PMID 27363015, 2016). "Last, Cdk inhibition by Ro3306 prevented accumulation of γ-H2AX and RPA2-P in response to CHK1 inhibitor AZD7762 in RBCC, suggesting that the increased initiation of DNA replication likely contributes to DSBs generation seen after CHK1 inhibition in radioresistant breast cancer cells." (PMID 27167194, 2016). "It has been reported that H2AX expression level is significantly higher in triple negative breast cancers (TNBC) than non-TNBC and in HER2 positive breast cancers versus those without HER2 overexpression." (PMID 32887437, 2020). "In estrogen receptor negative (ER−) breast cancer cells, combination of BOLD-100 with a PARP inhibitor, olaparib, induced significant inhibition of cell growth and xenografts and increased gamma-H2AX." (PMID 32947941, 2020). "UA induced DNA damage in breast cancer cells and this was accompanied by phosphorylation of ATM but not by phosphorylation of H2AX and 53BP foci formation (this study)." (PMID 28213701, 2017). "In comparison, in the two resistant luminal breast cancer cell lines BT474 and MCF7, treatment with an equitoxic dose of V158411 resulted in a decrease in Chk1 protein levels but not a subsequent increase in H2AX phosphorylation." (PMID 25104095, 2014).
lung carcinoma (64 papers, 2005 to 2025). "Moreover, FIBP-deficient lung cancer cells showed increases in γ-H2AX foci formation and the Olive tail moment, and these increases were partially reversed by overexpression of EME1." (PMID 37564211, 2023). "SENP1-siRNA-transfected cells treated with IR showed the highest protein level of γ-H2AX, suggesting that increased γ-H2AX expression may be one of the underlying mechanisms responsible for the increase in the radiosensitivity of lung cancer cells when SENP1 is inhibited." (PMID 24137315, 2013). "The delay in the repair of radiation-induced γ-H2AX foci following CTPI2 or octyl-D-2HG treatment alone or in combination with αKG supplementation was confirmed in A549 lung cancer cell line, giving comparable results." (PMID 38225236, 2024). "To elucidate the role of C1GALT1 in the DNA damage response of lung cancer cells, we quantified the number of γ-H2AX foci post-irradiation." (PMID 38662050, 2024). "It has been shown that overexpression of BTG2 in lung cancer cells leads to an increase in the number of DDR-inducedγ-H2AX lesions." (PMID 37547297, 2023). "In a rat silica-induced lung cancer model, the DNA damage response such as H2AX was evident in early preneoplasia." (PMID 37513116, 2023). "The repair kinetics differed between the two human lung cancer lines, with a reduction in γ‐H2AX and Rad51 foci at 4 h after irradiation in A549 cells compared to H460 cells, suggesting faster repair of DSB in A549 cells compared to H460 cells." (PMID 34636174, 2022). "Salvicine-induced DNA DSBs activate ATM and ATR kinases, as well as histone H2AX phosphorylation, in A549 lung cancer cells, which has been widely described in DSB-induced cellular responses." (PMID 35719997, 2022). "Of the human lung cancer lines, the H460 cell line had the most radiation‐induced ɣ‐H2AX foci, yet it showed the lowest increase in PLA foci after irradiation compared to A549 cells." (PMID 34636174, 2022). "We found that the proportion of PLA foci was inversely proportional to the number of γ‐H2AX foci in the treated human lung cancer lines." (PMID 34636174, 2022). "In the three lung cancer lines analysed herein, radiation induced a rapid, dose‐dependent formation of ɣ‐H2AX and Rad51 foci." (PMID 34636174, 2022). "In, 5 μM SAHA treatments of HFS normal human fibroblasts, A549 lung carcinoma, and LNCaP prostate cancer cells in vitro resulted in γ-H2AX foci formation, indicating HDACi are capable of inducing DSBs." (PMID 34513712, 2021). "Inhibition of KLC4 expression in the three types of lung cancer cell lines increased the expression level of γ-H2AX." (PMID 32457423, 2020). "The delays in disappearance of gamma ray-induced γ-H2AX foci following treatment with isoproterenol or PGE2 were also observed in A549 lung cancer cells." (PMID 32879366, 2020). "In this study, we applied the γ-H2AX assay to judge the radiosensitivity of lung cancer radiotherapy patients as normal or abnormal, based on kinetics of DNA damage repair." (PMID 32899789, 2020). "MiR-328 sensitizes cells to radiotherapy by targeting histone H2AX both in osteosarcoma and lung cancer; furthermore, in lung cancer mir-138 and miR-30a were also found as radiosensitizing agents via H2AX targeting." (PMID 31698689, 2019). "As expected, large γ-H2AX foci were formed in empty vector control A549 lung cancer cells 8 h after exposure." (PMID 30804322, 2019). "As a typical indicator of the amount of DNA damage, the level of γ-H2AX was examined in both NAT-F-treated lung cancer cells." (PMID 31619992, 2019).
lung carcinoma (continued). "In the present study, in different human lung cancer cells after exposure to IR, significant increases and delayed removal of γ-H2AX foci were observed in the Quinalizarin or si-CK2α pretreated group compared with those in the control group." (PMID 29170453, 2017). "The number of γ-H2AX foci was significantly increased in CDP138-depleted lung cancer cells after 4 and 24 h of IR exposure." (PMID 28880265, 2017). "In our study A549 human lung cancer cells were selected based on their very low background staining for classical RIF marker (γ-H2AX)." (PMID 27494855, 2016). "Taken together, these results indicated that H2AX phosphorylation regulates apoptosis in lung cancer cells via the miR-3196/PUMA pathway." (PMID 27780918, 2016). "In the present study, we used microarray assays to analyze the expression of miRNAs in lung cancer A549 cells in response to H2AX knockdown." (PMID 27780918, 2016). "Taken together, these data demonstrated that H2AX phosphorylation at Ser139 regulates miR-3196 expression during apoptosis of lung cancer cells." (PMID 27780918, 2016). "Cumulatively, our data indicates that H2AX phosphorylation regulates apoptosis in lung cancer cells through miR-3196/PUMA pathway." (PMID 27780918, 2016). "Here, we showed that H2AX knockdown in lung cancer A549 cells affected the expression of 16 microRNAs (miRNAs), resulting in the downregulation of 1 and the upregulation of 15 miRNAs." (PMID 27780918, 2016). "The signal intensity of both H2AX K134 methylation and γ-H2AX was notably higher in lung cancer tissues compared with normal tissues." (PMID 25487737, 2014). "To examine the relation between H2AX K134 methylation and γ-H2AX levels in clinical tissues, we conducted immunohistochemical analysis using tissue microarray comprising 154 cases of lung cancer." (PMID 25487737, 2014). "The results of the study showed that the inhibition of SENP1 markedly enhanced the radiosensitivity of lung carcinoma by promoting IR-induced cell cycle arrest, γ-H2AX expression and apoptosis." (PMID 24137315, 2013). "In this study, we showed that exogenous NPRL2 expression in NPRL2-negative tumor cells activated the DNA damage pathway, as evidenced by activation of ATM and NBS1 and increased γ-H2AX expression in lung cancer cells after NPRL2 treatment." (PMID 20700484, 2010). "Knockdown of MSI2 not only significantly increased the number of γ‐H2AX foci after irradiation, but also significantly increased the length of DNA tails in lung cancer cells, which indicated that knockdown of MSI2 increased the degree of DNA damage, or inhibited the DNA damage repair." (PMID 38645664, 2024). "Additionally, Western blotting showed that KRT7-AS overexpression elevated the levels of cisplatin-induced γ-H2AX in lung cancer cells, whereas silencing of KRT7-AS decreased the amount of cisplatin-induced γ-H2AX in A549 cells." (PMID 37185462, 2023). "Furthermore, KRT7-AS induced elevation of γ-H2AX levels in lung cancer cells was in a time-dependent manner; by contrast, silencing of KRT7-AS notably reduced the levels of γ-H2AX." (PMID 37185462, 2023). "The immunofluorescent staining indicated that KRT7-AS-overexpressing tumor cells were highly susceptible to cisplatin, as indicated by high levels of γ-H2AX, a classic marker of DNA strand breaks, conversely, KRT7-AS-silenced lung cancer A549 cells showed a decrease in γ-H2AX levels." (PMID 37185462, 2023). "Interestingly, in the two lung cancer cell lines the effects of genetic inhibition on the levels γ-H2AX were more pronounced compared to CTPI2 treatment, thus paralleling the differences in the effects of the two treatments on the D-2-HG accumulation." (PMID 35869047, 2022).